RN7SKP268 (RN7SK pseudogene 268)
Gene: Miscellaneous RNA gene on chromosome 6 (151,319,635 to 151,319,950, forward strand). Ensembl gene ENSG00000223039.
Homologues: Orthologues: chimpanzee 7SK (97% identical). Paralogues in human: RN7SKP180 (73% identical), 7SK (73% identical), RN7SKP184 (72% identical), RN7SKP250 (71% identical), RN7SKP170 (71% identical), RN7SKP185 (71% identical), RN7SKP30 (71% identical), RN7SKP176 (70% identical), RN7SKP255 (70% identical), RN7SKP269 (70% identical), RN7SKP203 (70% identical), RN7SKP9 (70% identical), and 283 more.